CCL4 (C-C motif chemokine ligand 4)
Diseases named in the same sentence as CCL4 in open-access papers (continued):
Sharing a sentence is not in itself a finding about the gene and the disease.
infection (continued). "MDV/CVI988 infection resulted in a substantial upregulation of CCL4 mRNA in the spleen of chickens, up to thirty-fold compared with uninfected chickens at 7 and 14 dpi." (PMID 36680047, 2022). "The other chemokines detected in this study involved in monocyte, T and NK cell recruitment were CCL2, CCL4 and CCL23, which were upregulated in the medium and high dose groups, resulting in an increased number of cells susceptible to infection." (PMID 35854219, 2022). "Infection led to robust induction of chemokine and interleukin genes, including Il1b, Il6, Ccl2, Ccl3, Ccl4, Ccl7, Cxcl1, Cxcl2, Cxcl5, Cxcl9, and Cxcl10, and related receptor genes, including Ccr1, Ccr4, Ccr5, Ccr5, Ccr7, Cxcr2, Cxcr5, Il1r2, and Il1rn." (PMID 35487885, 2022). "The CCL19 and CCL4 genes showed a similar trend, and they all peaked at 6 h (p < 0.05) and then decreased after infection and immunization." (PMID 36363767, 2022). "Although MDV/RB1B infection also positively regulated CCL4 transcription, the extent of upregulation was significantly less than that of MDV/CVI988 at 7 and 14 dpi." (PMID 36680047, 2022). "Our analyses indicated that despite the presence of baseline inflammation, 2 yr old mice had significantly lower induction of innate immune genes at 2 days post-infection, including Il6, Ccl4, Cxcl10, Rig-I, Irf7, Ifna2, Oas1b, and Mx2." (PMID 36679892, 2022). "We found that the CCL4/MIP1-β plasma levels were significantly higher during the acute phase of infection, increasing in the chronic phase." (PMID 35456119, 2022). "In response to the high viral titer infection, both CCL4 and CXCR5 were upregulated more robustly in young subjects compared to old subjects." (PMID 33796130, 2021). "MIP-1β, also known as CCL4, belongs to the chemokine family and is essential in immune responses to infection and inflammation." (PMID 34054345, 2021). "We noted that many genes were upregulated and preserved after infection, including Nkg7, Ccl5, Ifng, and Ccl4, which reinforces that MAIT cells had acquired an altered cellular state." (PMID 34272362, 2021). "In response to H1N1 or H3N2, there was a marked elevation of Ccl3, Ccl4, Ccl5, and Cxcl10 in young lung at day 3 post infection." (PMID 34829979, 2021). "After 6 h of infection, CCL4 gene, an important inflammatory chemokine, increased most obviously in monocyte-macrophage mRNA differential expression." (PMID 35046920, 2021). "VLV had a broader impact on gene expression in DCs after infection, upregulating genes related to inflammation (such as Ccl5, Ccl4, and IL12b), but also downregulating other genes." (PMID 34811393, 2021). "It was found that Rufomycin 4–7 treatment significantly decreased the Mabs-R-induced gene expression of various proinflammatory cytokines and chemokines (Tnfa, Il1b, Il6, Cxcl5, Ccl2, and Ccl4) in BMDMs at 6 h post-infection (hpi)." (PMID 34447358, 2021). "This is an expected reaction upon infection and responses with several of these chemokines and cytokines have also been monitored upon Eimeria infection in chickens, e.g. CCL4, IL-8, IL-1β and CSF3." (PMID 33536090, 2021). "Monocyte chemotactic protein 1 (MCP1 or CCL2), macrophage inflammatory protein 1 (MIP-1α or CCL3), and MIP-1β (CCL4) are crucial for macrophage migration/invasion and immune responses toward infection and inflammation." (PMID 33748112, 2021). "The in vivo effects of CCL4 seem complex and crucial for immune responses towards infection and inflammation." (PMID 32911750, 2020). "The chemotactic cytokines called macrophage inflammatory proteins (MIPs) include MIP-1α (also called CCL3) and MIP-1β (also called CCL4), which orchestrate immune responses to infection and inflammation." (PMID 32751118, 2020). "Treatment with proteasome inhibitor significantly inhibited the release of IL-1, IL-6, TNFα, MIP-1β (i.e. CCL4), and KC (i.e. CXCL1) at their peak time-points in Balb/c mice after infection with the highly pathogenic avian H5N1 influenza A virus." (PMID 33362782, 2020).
infection (continued). "The expression of CCL4 is high in the late phase of the active TB disease, but there are low levels of expression during early infection." (PMID 31749827, 2019). "CCL4 is an important chemoattractant for natural killer cells, monocytes and a variety of other immune cells, regulates immune response to pathogen infection." (PMID 31656701, 2019). "Various chemokine genes, responsible for the control and recruitment of immune cells to the site of infection (i.e., Ccl2, Ccl4, Ccl5, Ccl7, Ccl8, Ccl12, and Ccl19), were also significantly upregulated in the VACV-Wyeth infected brains on 4 d.p.i." (PMID 30759813, 2019). "We found that PK-15 cells treated with rapamycin plus 106, 107, and 108 CFU/mL of SH0165 showed a decreased IL-8 and CCL4 compared to SH0165 infection alone." (PMID 31106159, 2019). "Amongst cytokines, the genes for Cxcl9, Cxcl10, Cxcl13, Il-1β, Il-6, Tnf, Tnfsf10, IFN-γ, Ccl2, Ccl4, Ccl7, Ccl17, and Mif were highly up-regulated (ranging from 2- to 405-fold, p ≤ 0.05), whereas Cxcl12 and Cxcl14 were down-regulated during in vivo infection." (PMID 30857242, 2019). "By contrast, infection with the ΔgliP mutant caused an increase in mRNA levels of CXCL2, CCL3, and CCL4, chemokines that are chemotactic for neutrophils." (PMID 30052103, 2018). "LTB4/BLT1 axis is required for the synthesis of chemokines that recruits neutrophils (CXCL1 and CXCL2), monocytes (CCL2, CCL8, and CCL7) and T cells (CCL4) at both days 1 and 9 after infection." (PMID 30102746, 2018). "In fact, several of the cytokines seen here are the same neutrophil chemokines (Cxcl5, Ccl4, Cxcl1) and T-cell chemokines (Cccl5, Cxcl10, Ccl17) that were highlighted in the infection effect analysis." (PMID 30134832, 2018). "At 2 h post infection (p.i.), enhanced accumulation of mRNAs for Cxcl1, Cxcl2, Cxcl3, and Cxcl5, as well as Ccl3 and Ccl4, was evident (determined as differentially expressed using a 5% FDR)." (PMID 29636754, 2018). "TNF-α and CCL4 (MIP-1β) continued to be produced to significantly lower levels during Opal524R infection." (PMID 29138302, 2017). "We have previously shown that decidual cell culture supernatants, which contain CCL3 and CCL4, partially inhibit the infection of decidual mononuclear cells by blocking the HIV-1 entry." (PMID 27267272, 2016). "These cytokines are important for the activation of chemokines (such as MIP-1α/CCL3 and MIP-1β/CCL4) involved in leukocyte recruitment to the infection site for effective pathogen eradication." (PMID 26316174, 2015). "CCL3 and CCL4 are kept at the low levels until induction by inflammation or infection, but, in addition to being inducible by inflammatory and disease conditions, CCL18 is constitutively expressed at high levels in certain tissues." (PMID 25636406, 2015). "These gene lists also featured a number of inflammatory cytokines and chemokines involved in chemotaxis of myeloid and lymphoid cell types to the sites of infection (Ccl4, Ccl5, Ccl7, Ccl12, Cxcl9, Cxcl10)." (PMID 23853600, 2013). "Consistent with previous studies and associated with the classical activation M1 phenotype, transcription of TNFα (up to 5), CXCL10 (IP10), CCL2 (MIP1α), and other chemotactic cytokines such as CCL3 (up to 6.8) and CCL4 was upregulated following infection." (PMID 22928052, 2012). "those that are highly upregulated only by infection with virulent S. flexneri (CCL4, CCL20, IFN-γ, IL-1β, IL-4, IL-6, IL-8, IL-12/23p40, IL-21, TNF-α, CAP-18, LeukoP and COX-2); ii." (PMID 22675469, 2012). "Levels of the cytokine IL-6 and of the chemokines CXCL9, CXCL10, and CCL4 were significantly lower in vaginal washes one day after infection with HSV-2/gD compared with HSV-2/gD-Δ7-15." (PMID 21283640, 2011). "Such subepithelial pDCs are recruited and produce IFNα, IFNβ, MIP-1α (CCL3), and MIP-1β (CCL4) at day 1 of infection, which in turn promote inflammation and recruit T cell targets for infection." (PMID 21852945, 2011).
infection (continued). "At the chronic stage of SHIVSF164P4 infection, expression of the CCR5 ligands returned to pre-infection levels (CCL4 and CCL5), or even increased (CCL3) in all three GALTs." (PMID 17684570, 2007). "By PID 180, expression of CC-chemokines returned to pre-infection levels (CCL4 and CCL5), or even increased (CCL3)." (PMID 17684570, 2007). "Notably, cytokine family members Ccl2, Ccl3, Ccl4, Ccl5, Ccl7, Ccl9, and Ccl22 were also significantly activated following infection." (PMID 40539063, 2025). "Pro-inflammatory cytokines and chemokines, including TNF-α, CSF3 and CCL4, were upregulated in both infection groups, alongside genes involved in immune cell adhesion and inflammatory responses (SELE), as well as stress response mediators such as HSP70 and PNLIPRP3." (PMID 41435987, 2025). "Therefore, the levels of TNF-α, IL-6, IFN-γ, and CCL4 in serum were measured at 4, 24, and 48 h post infection." (PMID 40872776, 2025). "CCL4, also known as macrophage inflammatory protein-1β (MIP-1β), is produced by macrophages, dendritic cells, lymphocytes, and epithelial cells in response to infection and has been linked to acute neutrophilic inflammation." (PMID 41303221, 2025). "4T1 cell infection with SFV upregulated the amount of CCL4 and CXCL10 (p < 0.05)." (PMID 40547518, 2025). "Similarly, after BF.7 infection of M1 macrophages, the administration of IL‐37 led to an approximately 21% decrease in Ccl4 mRNA expression and an approximately 15% reduction in Ccl3 mRNA expression." (PMID 40452816, 2025). "Furthermore, macrophage inflammatory proteins such as MIP-1α (CCL3) and MIP-1β (CCL4) play a major role in immune responses against infection or inflammation in response to external stimuli." (PMID 38494495, 2024). "The CCL4 gene regulates the immune response to infection and inflammation." (PMID 39051372, 2024). "Other T cell populations and NK cells were also found to express both Ccl4 and Ccl5 upon infection." (PMID 38236930, 2024). "Macrophage inflammatory protein-1beta (MIP-1β/CCL4) is the essential chemotactic cytokine in the immune response against infection and inflammation; A chemokine (chemotactic factors) is a small cytokine that attracts other cells to a local area to exert its biological effects." (PMID 36999058, 2023). "For example, mature DCs could produce CCL3 and CCL4 after Mtb infection, which further recruit immature DCs to the site of infection and replace the mobilized population." (PMID 36315280, 2023). "CCL4 is crucial for the immune responses to infection and inflammation." (PMID 36011367, 2022). "However, an enhanced upregulation of 9 genes, all involved in the NF-kB pathway (CCL2/MCP1, CCL20, CCL4, CXCL2/MIP2α, IL1A, NFKBIA, PTX3, TNFA, TNFAIP3), was observed after infection with D26 variants, in comparison to the WT." (PMID 33399033, 2021). "We found that many cytokines messenger RNAs (mRNAs), including Il1b, Il5, Il6, Il10, Il12a/Il12p70, Ifng, Ccl4, Ccl5, Tnfa, Gcsf, Cxcl1, Il1a, and Il3, were significantly induced upon B.1.351 infection in the lungs of hACE2 transgenic, BALB/c, and C57BL/6 mice." (PMID 34907154, 2021). "On the other hand, we noted increased levels of monocyte/macrophage associated chemokines CCL2/MCP1 and CCL4/MIP1β in rAd5-YFV vaccine-immunized mice that were not seen in controls in response to CO92 infection." (PMID 33514747, 2021). "The significant upregulation of CCL4 in response to CVI988 infection in lymphocytes further postulates that CCL4 might be a fundamental gene in MDV-mediated early cytolytic infection." (PMID 32210095, 2020). "Moreover, genes such as Ifr9, Ifr8, Ifr7, CSF2RA, STAT1, and STAT2 were expressed to a greater extent in the PmQ infection group than PmCQ2, and Il22, Il6, Nos2, Ccl4, Ccl5, Ifr1, Socs1, and Socs3 were increased only in PmQ infected chickens rather than PmCQ2." (PMID 32851030, 2020). "Upon infection of cells in vitro, the rVACV produced mKate, as well as ccl4 mRNA and protein." (PMID 31603920, 2019).
infection (continued). "In addition, macrophage depletion led to reduced production of CXCL1, and CCL4 24 hours after infection." (PMID 30102746, 2018). "Additionally, closer examination of the leading-edge genes of significant chemokine gene sets shows significant representation of neutrophil chemokines (Cxcl5, Ccl4 and Cxcl1), suggesting strong phase:infection interaction effect." (PMID 30134832, 2018). "However, our results demonstrated that the inflammatory chemokines in chickens, CCL4 and CCL5, were induced by cNK-2 in innate immune cells, suggesting a role of this peptide in association with inflammatory response-mediated infections." (PMID 28332637, 2017). "Notably, TNF-α and CCL4 levels were significantly lower during Opal524R infection at days 1 and 2 postinfection." (PMID 29138302, 2017). "RT-qPCR analysis demonstrated that infection with both strains of T. cruzi resulted in increased expression of Ccl4 and Edn2 genes compared with control (p = 0.0014 and p = 0.0111, respectively), whereas Gzmd was down-regulated in both infected groups (p = 0.0047)." (PMID 28273076, 2017). "However, we observed that after infection the transcript levels of Ccl4 and Ccl5 were similarly up-regulated in the lungs of CAST/EiJ as for 129S1/SvImJ and C57BL/6J (data not shown)." (PMID 26921172, 2016). "In contrast, we noted an increase in a subset of Th17-associated cytokines in the BAL, specifically IL-17, IL-6, G-CSF, and CCL4, and elevated levels of these cytokines were sustained even after the majority of the IFNγ response had subsided, i.e. day 14 post infection." (PMID 25849970, 2015). "Such reagents will allow the critical evaluation of whether and how IDE activity will impact CCL3 and CCL4-mediated immune responses during inflammation and infection and how such effects would impact IDE-based therapy." (PMID 25636406, 2015). "Moreover, L. major amastigotes did not induce the production of the proinflammatory cytokine TNF and the chemokines CCL3 and CCL4, which is in contrast to the higher production during promastigote infection." (PMID 25294956, 2014). "Notably, protein levels for CCL4 and CXCL8 were >20-fold and >40-fold higher respectively in choriodecidua from women with infection-associated PTL than idiopathic PTL and both strongly correlated with neutrophil abundance." (PMID 23451115, 2013). "CCL4 was expressed at significantly higher levels in livers of WSX-1−/− mice compared to WT mice on day 7 of infection, whereas CCL4 and CCL5, both ligands for CCR5, were expressed at 5–10-fold higher levels in livers of WSX-1−/− mice compared to WT mice on day 14 of infection." (PMID 24244314, 2013). "The expression of 277 genes was induced >2-fold in a statistically significant manner by infection with Mtb:Δ-sigH at the 0 hr time-point Some of the genes with the greatest induction included CCL4 (17.6-fold), CXCL2 (10-fold), CCL7 (6.5-fold) and CCL20 (4.3-fold)." (PMID 22235255, 2012). "In our model, some chemokines reported to be part of the "1st and 2nd waves" of chemokine expression by DC cells, specifically Xcl1, Cxcl9, Cxcl16, Ccl1, Ccl2, Ccl3, Ccl4, Ccl5, Ccl7 and Ccl8 are expressed at increased levels in lung i.n. samples at 3 weeks post-infection." (PMID 20942964, 2010). "Additionally, L. major internalization delays the neutrophil apoptotic death program and induces CCL4 release, which recruits macrophages to the infection site." (PMID 20559550, 2010). "This conclusion is supported, at least in part, by the results of Sukumaran and colleagues, who reported the upregulated expression of chemokine genes encoding CXCL1, CXCL2, CXCL3, CXCL8, CCL3, CCL4 and CCL20 after infection of PMN with Anaplasma phagocytophilum." (PMID 17875202, 2007). "Importantly, dormant C. neoformans retained the ability to provoke gene regulation of monocyte chemotaxis, leading to the secretion of CCL2, chemokine associated with cryptococcal granuloma formation; and CCL4, which was particularly more secreted in this infection." (PMID 38033163, 2023).